EGFR (epidermal growth factor receptor)
Diseases named in the same sentence as EGFR in open-access papers (continued):
Sharing a sentence is not in itself a finding about the gene and the disease.
non-small cell lung carcinoma (continued). "Lung adenocarcinoma (LUAD) is the most common subtype of non-small cell lung cancer, with EGFR mutations serving as key oncogenic drivers." (PMID 41164195, 2025). "In non-small cell carcinoma, GA inhibits the activation of the epidermal growth factor receptor (EGFR) and prevents coactivator-associated arginine methyltransferase 1 (CARM1) from binding to proline, glutamate, and leucine-rich protein 1 (PELP1)." (PMID 40786042, 2025). "Clinical trials have demonstrated the efficacy of osimertinib against brain metastases in patients with EGFR-mutated non-small cell lung cancer (NSCLC) who have experienced disease progression with first- and second-generation EGFR-TKIs." (PMID 41446706, 2025). "Osimertinib, a third-generation EGFR tyrosine kinase inhibitor, played a crucial role in the treatment of EGFR-mutated non-small cell lung cancer." (PMID 40661081, 2025). "EGFR is closely associated with the development and advancement of solid tumors, establishing itself as a crucial therapeutic target, particularly in non-small-cell lung carcinoma (NSCLC), glioblastoma, colorectal, breast, gastroesophageal cancers and so on." (PMID 40849468, 2025). "This LB CGP test was originally approved for the identification of EGFR mutations in patients with non-small cell lung cancer (NSCLC), in particular deletions in exon 19, L858R in exon 21, or T790M in exon 20, to predict the benefit from osimertinib." (PMID 40740670, 2025). "The top 10 institutions published articles related to tumor microenvironment in non-small cell lung cancer with epidermal growth factor receptor mutation." (PMID 40181972, 2025). "Osimertinib is a third-generation epidermal growth factor receptor tyrosine kinase inhibitor (EGFR-TKI) used in the treatment of EGFR mutation-positive advanced non-small cell lung cancer." (PMID 39917172, 2025). "Epidermal growth factor receptor (EGFR) tyrosine kinase inhibitors are commonly used to treat non-small cell lung cancers with EGFR mutations, but drug resistance often emerges." (PMID 39747003, 2025). "The overexpression or mutations of EGFR are commonly associated with several types of cancer, including non-small cell lung cancer, colorectal cancer, and glioblastomas." (PMID 39996991, 2025). "Mutations in the EGFR gene, particularly those occurring in the kinase domain, are frequently observed in various malignancies—including non-small cell lung cancer (NSCLC) and glioblastoma, where they often act as key oncogenic drivers." (PMID 40650000, 2025). "Dysregulation of EGFR signaling is frequently observed in non-small cell lung cancer (NSCLC) and is associated with poor prognosis." (PMID 40210802, 2025). "The Top 10 journals and co-cited journals related to tumor microenvironment in non-small cell lung cancer with epidermal growth factor receptor mutation." (PMID 40181972, 2025). "Our study reveals a high frequency of occult EGFR mutations (Exon 19 deletion and Exon 21 L858R mutation) in non-small cell lung cancer (NSCLC) patients, particularly among male smokers and female non-smokers." (PMID 39429333, 2024). "It is generally administered for the standard treatment of patients with previously untreated EGFR-mutated advanced non-small-cell lung cancer (NSCLC)." (PMID 38391832, 2024). "For instance, the Cobas EGFR mutation Test v2 (Roche Diagnostics) was the first approved ctDNA-based companion diagnostic test for non-small cell lung cancer (NSCLC)." (PMID 40026562, 2024). "The epidermal growth factor receptor (EGFR) mutation was thefirst driver gene discovered for non-small cell lung cancer (NSCLC)(Attili) (John)." (PMID 38869202, 2024). "In non-small cell lung cancer (NSCLC) cell lines susceptible to EGFR mutations, SCD1 expression is elevated, thereby increasing the intracellular LD content." (PMID 39403606, 2024). "Our study focused on patients with EGFR-mutated non-small cell lung cancer receiving tyrosine kinase inhibitor therapy." (PMID 39682169, 2024).
non-small cell lung carcinoma (continued). "We conducted a comprehensive case study involving 457 non-small cell lung cancer patients with EGFR mutations treated with EGFR tyrosine kinase inhibitors." (PMID 39211737, 2024). "In non-small cell lung cancer, for example, it has been described that patients with EGFR mutations who have been treated with tyrosine kinase inhibitor (TKI) therapy are more likely to develop leptomeningeal disease." (PMID 39678503, 2024). "Recent findings in non-small cell lung cancer (NSCLC) indicate that EGFR gene mutations directly correlate with the increased expression of PD-L1." (PMID 38541123, 2024). "Despite initial response to epidermal growth factor receptor (EGFR) tyrosine kinase inhibitors (TKIs), most patients with non-small cell lung cancer (NSCLC) harboring EGFR activating mutations inevitably develop resistance after approximately one year." (PMID 38903714, 2024). "An example of incurable cancer with genetic mutations and rearrangements is epidermal growth factor receptor (EGFR) mutation in non-small cell lung cancer." (PMID 38428972, 2024). "It is an effective therapeutic agent for non-small cell lung cancer (NSCLC) associated with active mutations in EGFR, mainly in exons 19 (deletion) and 21 (L858R)." (PMID 39204145, 2024). "The kinase domain of the epidermal growth factor receptor (EGFR) is an established drug target in non-small cell lung cancer (NSCLC) where oncogenic mutations often predict clinical responsiveness to treatment with certain TKIs37." (PMID 38378740, 2024). "Lung adenocarcinoma (LUAD) is the most common pathological type of non-small-cell lung cancer, which has a frequency of approximately 45% cases with mutations in EGFR." (PMID 38978091, 2024). "The same applies to cells derived from non-small cell lung cancer with an upstream epidermal growth factor receptor (EGFR) mutation." (PMID 38314086, 2024). "Epidermal growth factor receptor (EGFR) tyrosine kinase inhibitors (TKIs) and EGFR-TKI combination treatments have become the standard first-line treatments for EGFR-mutated non-small cell lung cancer (NSCLC) patients." (PMID 39533233, 2024). "Ten percent of non-small cell lung cancer patients with epidermal growth factor receptor (EGFR) mutations harbor uncommon variants." (PMID 39166093, 2024). "Somatic mutations in the EGFR gene occur in about 50% of non-small cell lung cancers, with the T790M mutation significantly contributing to secondary resistance against EGFR-TKI drugs." (PMID 39160638, 2024). "Some EGFR inhibitors, such as osimertinib, can only inhibit PD-L1/2 in EGFR-mutated non-small cell lung cancer." (PMID 38826132, 2024). "In this study, we aimed to develop a fusion model that combines clinical, radiomic, and deep learning data to predict EGFR mutation subtypes in non-small cell lung cancer (NSCLC) patients." (PMID 39619439, 2024). "Third-generation tyrosine kinase inhibitors are the first-line gold standard in treating advanced non-small-cell lung cancer bearing common EGFR mutations, but data documenting clinical efficacy in uncommon mutations are currently limited." (PMID 39062751, 2024). "Approximately 60% of Asian populations with non-small cell lung cancer (NSCLC) harbor epidermal growth factor receptor (EGFR) gene mutations, marking it as a pivotal target for genotype-directed therapies." (PMID 39650554, 2024). "Osimertinib is used as the first-line therapy for patients with epidermal growth factor receptor (EGFR)-mutated non-small cell lung cancer (NSCLC)." (PMID 38536543, 2024). "For instance, EGFR inhibitors like erlotinib and gefitinib have proven effective in treating non-small cell lung cancer with EGFR mutations, showcasing the precision of TKIs in addressing specific cancer subtypes." (PMID 39465760, 2024). "The prognostic utility of laboratory markers in patients with non-small cell lung cancer (NSCLC) harboring EGFR mutations treated with tyrosine kinase inhibitors (TKIs) is an ongoing area of research." (PMID 39483887, 2024).
non-small cell lung carcinoma (continued). "In EGFR-mutated non-small cell lung cancer, Qianet al. identified a novel E3 ubiquitin ligase, MARCH8, which can mediate the degradation of PD-L1 induced by EGFR inhibition." (PMID 38826132, 2024). "EGFR amplification (Amp) and mutations have been identified as driving events for multiple cancers, non-small cell lung cancer (NSCLC), breast cancer and GBM in particular." (PMID 38595969, 2024). "Epidermal growth factor receptor tyrosine kinase inhibitors (EGFR TKIs) are the standard treatment for non-small cell lung cancer (NSCLC) patients who harbor the EGFR mutation." (PMID 39555307, 2024). "Epidermal growth factor receptor (EGFR) is a tyrosine kinase often mutated in non-small-cell lung cancer and other solid tumors." (PMID 39330321, 2024). "The epidermal growth factor receptor (EGFR) gene is the most frequently mutated gene in non-small cell lung cancer." (PMID 39682169, 2024). "Interstitial lung disease (ILD) or pneumonitis caused by epidermal growth factor receptor (EGFR) tyrosine kinase inhibitors (TKI) or immune checkpoint inhibitors (ICI) is a major concern in the treatment of non-small cell lung cancer (NSCLC)." (PMID 38919534, 2024). "Furmonertinib is the standard treatment option in the first-line setting for advanced non-small cell lung cancer (NSCLC) with sensitive epidermal growth factor receptor (EGFR) mutations in China." (PMID 38454923, 2024). "Although no benefit in overall survival was demonstrated, following these trials, both products were registered in the first-line setting for treating EGFR mutation-positive stage IIIB/IV non-small cell lung cancer." (PMID 38605928, 2024). "Another clinical trial was performed in non-small-cell lung cancer (NSCLC) patients with positive epidermal growth factor receptor (EGFR) mutation." (PMID 39161385, 2024). "Some studies have identified targeted therapies for EGFR (epidermal growth factor receptor), which exhibits abnormal mutation activity in non-small cell lung cancer, such as gefitinib, erlotinib, and afatinib." (PMID 38167018, 2024). "EGFR was the most commonly identified driver mutation in non-small cell lung cancer (29% of cases, n = 86)." (PMID 39061145, 2024). "Activating mutations in the EGFR gene were first identified in non-small cell lung cancers (NSCLC) in 2004, marking one of the most significant advancements in understanding the molecular biology of these tumors." (PMID 39199653, 2024). "Most non-small cell lung cancers (NSCLCs) with activating mutations in epidermal growth factor receptor (EGFR) respond to EGFR-tyrosine kinase inhibitors (EGFR-TKIs)." (PMID 39660536, 2024). "Recognized as a key therapeutic target in oncology, EGFR is frequently mutated in non-small-cell lung cancer (NSCLC)." (PMID 39743996, 2024). "There are two common hotspot mutations in the structural domain of EGFR kinase: exon 19 deletion and exon 21 L858R mutation; exon 19 deletion variants account for approximately 45–50% of EGFR variants in non-small cell lung cancer." (PMID 38902753, 2024). "EGFR is a powerful oncogene, and EGFR activation mutations are the key determinants of carcinogenic transformation and therapeutic targets for non-small cell lung cancer." (PMID 39130630, 2024). "The Epidermal Growth Factor Receptor (EGFR) is frequently found to be mutated in non-small cell lung cancer." (PMID 38503739, 2024). "This study examined the real-world effectiveness of osimertinib, a third-generation tyrosine kinase inhibitor, on EGFR-mutated non-small-cell lung cancer." (PMID 39518004, 2024). "The primary molecular subtype in driver gene-positive non-small cell lung cancer (NSCLC) involves the activation mutation of epidermal growth factor receptor (EGFR)." (PMID 38566102, 2024). "Osimertinib is a third-generation tyrosine kinase inhibitor (TKI) that has emerged as a standard treatment in non-small cell lung cancer (NSCLC) with epidermal growth factor receptor (EGFR) mutation." (PMID 39310509, 2024).
non-small cell lung carcinoma (continued). "Both the NCCN and CSCO guidelines recommend the use of EGFR-TKIs as first-line treatment for advanced non-small cell lung cancer patients with EGFR mutations." (PMID 39196297, 2024). "We therefore anticipate that this PDC can be successfully utilized not only for the treatment of non-small cell lung cancer but also for other cancers with intracellular EGFR mutations." (PMID 39771591, 2024). "The EGFR tyrosine kinase inhibitor osimertinib has been approved for the first-line treatment of EGFR-mutated Non-Small Cell Lung Cancer (NSCLC) patients." (PMID 38499619, 2024). "Another study examined the impact of feature harmonization on radio-genomics analysis for the prediction of KRAS and EGFR mutations from non-small cell lung cancer from PET/CT images." (PMID 38575814, 2024). "Epidermal growth factor receptor (EGFR) mutations occur in almost 10–15% of patients affected by non-small cell lung cancer (NSCLC) in the western world and in 30–40% of the Asiatic population." (PMID 38966183, 2024). "For example, instances of mutated EGFR accompanied by ligand amplification have been discerned in breast cancer, colorectal cancer, cutaneous squamous cell carcinoma, and non-small cell lung cancer (NSCLC)." (PMID 39668367, 2024). "Agents specifically targeting EGFR have proven effective in treating advanced non-small cell lung cancer and other diseases with EGFR mutations." (PMID 38557672, 2024). "For instance, ctDNA has proven to be particularly valuable in non-small-cell lung cancer, where it helps detect EGFR mutations, enabling clinicians to tailor targeted therapies more effectively and monitor patients’ responses to treatment." (PMID 39682234, 2024). "The discovery of mutations in the epidermal growth factor receptor (EGFR) gene allowed for the development of tyrosine kinase inhibitors (TKIs) as first-line treatment for advanced/metastatic non-small-cell lung cancer harboring EGFR mutations." (PMID 39122703, 2024). "Although second-generation agents are effective in patients with non-small cell lung cancer (NSCLC) with EGFR mutations, they are associated with relatively low progression-free survival (approximately 10 months) and side effects such as rash and diarrhea." (PMID 39291996, 2024). "The findings showed that 3D-T1WI enhanced imaging omics of brain metastases from non-small cell lung cancer had high diagnostic efficacy and net clinical benefit in determining EGFR mutation status." (PMID 38773634, 2024). "In the past decade, non-small cell lung cancer (NSCLC) patients with epidermal growth factor receptor (EGFR) mutations, such as exon 19 deletions and exon 21 L858R point mutations, have benefited from EGFR tyrosine kinase inhibitors (TKIs)." (PMID 38658988, 2024). "EGFR-TKIs is indicated for patients with a diverse array of tumors carrying EGFR mutations, encompassing non-small cell lung cancer (NSCLC), pancreatic cancer, glioblastoma, and head and neck squamous cell carcinoma." (PMID 39211774, 2024). "Mutations in the epidermal growth factor receptor (EGFR) kinase domain are common in non-small cell lung cancer." (PMID 38363422, 2024). "Real-world evidence for patients with advanced EGFR-mutated non-small cell lung cancer (NSCLC) in Canada is limited." (PMID 38668049, 2024). "EGFR-activating mutations are prevalent in non-small cell lung cancer (NSCLC), particularly in East Asia, where the incidence rate is approximately 30–40%3." (PMID 38689087, 2024). "Blocking glutamine metabolism in EGFR-mutated non-small cell lung cancer significantly increases sensitivity to almonertinib." (PMID 39609317, 2024). "Targeted therapy has significantly prolonged survival of non-small cell lung cancer (NSCLC) patients carrying common EGFR mutations, but the standard care for patients with rare mutations has not been well established." (PMID 39679364, 2024).
non-small cell lung carcinoma (continued). "These include the Cobas EGFR mutation test V2, which can identify EGFR mutations in non-small cell lung cancer, and the Therascreen PIK3CA RGQ PCR kit, which can identify PIK3CA mutations in breast cancer." (PMID 39219215, 2024). "In patients with non-small cell lung cancer (NSCLC) with epidermal growth factor receptor (EGFR) mutation, EGFR tyrosine kinase inhibitors (TKIs) yield significant treatment responses." (PMID 39298415, 2024). "Among Non-Small Cell Lung Cancer (NSCLC) patients a notable proportion of patients will have a mutation in the EGFR gene." (PMID 38468224, 2024). "L858R mutation and exon 19 deletion are the most common EGFR-activating mutations in non-small cell lung cancer (NSCLC) patients." (PMID 39967270, 2024). "Treatment success of Epidermal Growth Factor Receptor (EGFR) mutated Non-Small Cell Lung Cancer (NSCLC) with Tyrosine Kinase Inhibitors (TKIs) is hampered by treatment resistance development." (PMID 38363422, 2024). "For instance, in non-small-cell lung cancer, 24% of clinically significant EGFR T790M resistance mutations were found at variant allele frequencies below 5%, underscoring the necessity for sensitive detection methods." (PMID 39596624, 2024). "Develop a radiomics nomogram that integrates deep learning, radiomics, and clinical variables to predict epidermal growth factor receptor (EGFR) mutation status in patients with stage I non-small cell lung cancer (NSCLC)." (PMID 38982267, 2024). "A mutation, or damage, in an EGFR gene causes the tumorgenesis, such as in EGFR-positive non-small cell lung cancer (NSCLC) patients." (PMID 38279998, 2024). "EGFR gene upregulation has been linked with multiple cancer types, such as breast cancer, non-small cell lung cancer (NSCLC), and head and neck squamous cell carcinoma." (PMID 38505421, 2024). "Non-small-cell lung cancer (NSCLC) frequently harbors mutations in the epidermal growth factor receptor (EGFR), with exon 20 insertions comprising 1–10% of these mutations." (PMID 38892105, 2024). "Approximately 20% of individuals diagnosed with non-small cell lung cancer (NSCLC) harbor a distinct genetic mutation in the epidermal growth factor receptor (EGFR) gene, referred to as an activating somatic mutation." (PMID 38238740, 2024). "Epidermal growth factor receptor EGFR inhibitors are widely used as first line therapy for the treatment of non-small-cell lung cancer (NSCLC) in patients harboring EGFR mutation." (PMID 38625872, 2024). "Statins were also associated with prolonged survival in non-small cell lung cancer (NSCLC) patients treated with epidermal growth factor receptor tyrosine kinase inhibitor (EGFR-TKI)s." (PMID 38478558, 2024). "For instance, the presence of exosomal EGFR mutations in patients with non-small cell lung cancer can provide a crucial basis for the utilization of specific EGFR inhibitors, thereby enabling highly personalized and effective treatment strategies." (PMID 40026560, 2024). "Mutations in epidermal growth factor receptor (EGFR) occur in 12–15% of European patients with non-small cell lung cancer (NSCLC) and 30–50% in Asian patients with NSCLC1,2." (PMID 38778166, 2024). "Epidermal growth factor receptor (EGFR)-tyrosine kinase inhibitors (TKIs) are currently the most effective treatment for advanced non-small cell lung cancer (NSCLC) with EGFR mutations and can result in marked tumor shrinkage." (PMID 38265672, 2024). "Epidermal growth factor receptor (EGFR) driver mutations are crucial for treatment decisions for patients with non-small cell lung cancer (NSCLC)." (PMID 38238401, 2024). "The success of first-generation EGFR inhibitors, such as gefitinib and erlotinib, in the treatment of EGFR-mutated non-small cell lung cancer has underscored the therapeutic potential of EGFR-targeted agents." (PMID 39596465, 2024).